ILK (integrin linked kinase)
Diseases named in the same sentence as ILK in open-access papers (continued):
Sharing a sentence is not in itself a finding about the gene and the disease.
colitis (continued). "Myeloid-ILK deficient mice showed enhanced tumour infiltration of CD8+ T cells and reduced tumour infiltration of FOXP3+ T cells in colitis-associated and APCmin/+-driven CRC, respectively, with an overall elevated CD8+/FOXP3+ ratio suggesting an anti-tumour immune phenotypes." (PMID 38077324, 2023). "Moreover, intestinal epithelial cell (IEC) -specific ILK deletion in mice reduced both colitis and CAC, suggesting an integral role for IEC-ILK in intestinal inflammation and CRC." (PMID 38077324, 2023). "Since our lab has shown that ILK expression in myeloid cells promotes neutrophil infiltration in experimental mice colitis, we posited that ILK might be involved in immune infiltration in the TME." (PMID 35692780, 2022). "Since ILK mediates activation of the TLR4/NF-κB/TNF-α signaling pathway by LPS (a TLR4 agonist) in colitis, it is possible that ILK could have an impact on regulating the activities of different TLRs in cancer." (PMID 34163519, 2021). "Indeed, we found that protection of ILK-ko mice from colitis correlated with a relative increase in Foxp3+ Tregs in both the colon and in mesenteric lymph nodes." (PMID 21806815, 2011). "In order to investigate this hypothesis we investigated the role of epithelial cell-specific expression of ILK in acute and chronic models of colitis." (PMID 21806815, 2011). "Conditional intestinal epithelial cell ILK knockout mice were used for assessment of acute and chronic dextran sodium sulfate (DSS) -induced colitis." (PMID 21806815, 2011). "Our findings indicate that C rodentium -induced colitis is impaired in mice lacking expression of ILK within the colonic epithelium." (PMID 24024606, 2013).
Hepatic fibrosis (7 papers, 2017 to 2025). The presence of excessive fibrous connective tissue in the liver. "Tb4-overexpressing transgenic mice treated with CCl4 were susceptible to the development hepatic fibrosis with higher levels of ILK, pGSK3b, and Hh activity, as compared with wild-type mice." (PMID 28630423, 2017). "Abolitions of HI activation were noted for mTOR signaling, hepatic fibrosis signaling, and ILK signaling." (PMID 33923910, 2021). "Studies have shown that ILK is widely involved in impaired tissue repair, include nerve fibers, myocardium, and hair follicles, and plays an important regulatory role in the processes of renal interstitial fibrosis, pulmonary fibrosis and liver fibrosis." (PMID 34118875, 2021). "To investigate whether enhanced expression of Tb4 increased Hh signaling and contributed to the excessive hepatic fibrosis in the CCl4-treated Tb4-Tg mice, we examined the expression levels of ILK, GSK3B and Hh signaling." (PMID 28630423, 2017). "In conclusion, the present study demonstrated that TB4 enhanced the activation of SMO-GLI2 by regulating the expression of ILK and pGSK3b, as well as interacting with SMO and GLI2, thereby promoting HSC activation and liver fibrosis." (PMID 28630423, 2017). "Hepatic fibrosis/hepatic stellate cell activation, HIPPO signaling, natural killer cell signaling, galactose degradation (Leloir Pathway) and ILK signaling were identified as the top canonical pathways unique to the 599 focus genes in the BCNS keratinocytes samples after rapamycin treatment." (PMID 30858923, 2019). "Given that GSK3B is one of the targets of ILK29, 46, it is possible that TB4-dependent activation of ILK and concomitant repression of pGSK3B increases Hh signaling by promoting the activation of SMO-GLI2, resulting in the activation of quiescent HSCs during liver fibrosis." (PMID 28630423, 2017).
Hyperglycemia (7 papers, 2017 to 2024). An increased concentration of glucose in the blood. "Accordingly, these results demonstrated that ILK gene-modified BMSCs may provide a protective effect for the ischemia bladder tissues against massive apoptosis caused by hyperglycemia." (PMID 32650831, 2020). "Hyperglycemia could downregulate expression of integrin α3β1 in both human and rat, as well as trigger activation of integrin-linked kinase (ILK)." (PMID 28791309, 2017). "Hyperglycemia evokes podocyte EMT through several molecular mechanisms including TGF-β/Smad pathway, Wnt/β-catenin signaling pathway and integrins/integrin-linked kinase signaling pathway." (PMID 33202982, 2020). "Hyperglycemia induces podocyte EMT through several molecular mechanisms such as TGF-β/Smad classic pathway, integrin-linked kinase signaling pathway and NF-κB signaling pathway." (PMID 33202982, 2020). "Considering the unclear effects of ILK on cell proliferation and angiogenesis in vivo, we suspect that ILK has a protective effect on hyperglycemia-induced apoptosis." (PMID 32650831, 2020). "Regarding ILK, hyperglycemia and hyperinsulinemia were observed in ILK-depleted mice." (PMID 38543160, 2024).
non-small cell lung carcinoma (7 papers, 2005 to 2022). A group of at least three distinct histological types of lung cancer, including non-small cell squamous cell carcinoma, adenocarcinoma, and large cell carcinoma. "Highly expressed ILK was an independent poor prognostic factor for progression-free survival in patients with non-small-cell lung cancer (NSCLC), while the knockdown of ILK gene made lung squamous cell carcinoma sensitive to TKI therapy." (PMID 33921219, 2021). "Over-expression of ILK has a close relationship with prostate cancer, high-grade gastric cancer, and NSCLC (non-small cell lung cancer)." (PMID 27576342, 2016). "Increased ILK expression is correlated with progression of several tumor types, but the expression of ILK has not been investigated in patients with non-small cell lung cancers (NSCLCs)." (PMID 15631637, 2005).
thyroid cancer (7 papers, 2015 to 2025). "Several signalling pathways were affected, including calcium, integrin-linked kinase, and thyroid cancer signalling, and the peroxisomal proliferator-activated receptor network." (PMID 26492889, 2015). "In the present study, calcium, integrin-linked kinase and thyroid cancer signalling were the top three canonical pathways generated using the IPA comparison analysis tool." (PMID 26492889, 2015). "Silencing of the ILK decreased the phosphorylation of Akt and prevented the migration of thyroid cancer cells." (PMID 27034956, 2016). "Indeed, previous studies have demonstrated that the increased ILK expression in poorly differentiated thyroid cancer and confirmed the relationship between ILK overexpression and poor prognosis." (PMID 30636169, 2019). "In contrast, thyroid cancer signalling, CXCR4, ILK, IL-8, IL-3, JAK/STAT and mTOR signalling pathways were significantly enriched in GWASLN6." (PMID 41520521, 2025). "In the GWASLN6, thyroid cancer signalling, as well as the CXCR4, ILK, IL-8, IL-3 and the JAK/STAT signallings, were statistically enriched." (PMID 41520521, 2025). "Because its expression was previously assessed in several thyroid cancer cell lines, but it was expressed at very low levels in TPC1 and BCPAP cells, the role of ILK in migration, invasion, and modulation of EMT-related proteins was not further investigated in these cells by the authors." (PMID 33238381, 2020).
endothelial dysfunction (6 papers, 2007 to 2024). In vascular diseases, endothelial dysfunction is a systemic pathological state of the endothelium (the inner lining of blood vessels) and can be broadly defined as an imbalance between vasodilating and vasoconstricting substances produced by (or acting on) the endothelium. "In this regard, our group demonstrated that ILK activity is involved in monocyte adhesion and migration induced by uremic toxins, which might cause endothelial dysfunction." (PMID 38734696, 2024). "Decreased ILK levels in vascular endothelium induce endothelial dysfunction by uncoupling eNOS, and decreased levels of ILK are involved in aortic valve calcification." (PMID 38534325, 2024). "Integrin-linked kinase (ILK) prevents endothelial nitric oxide synthase (eNOS) uncoupling and, thus, endothelial dysfunction." (PMID 37452166, 2023). "Together, these results demonstrate that NO production in hVECs also depends on ILK expression and that an endothelial dysfunction is an early event after ILK expression decreases." (PMID 36139812, 2022). "Since ILK deletion can lead to endothelial dysfunction and to study whether the cardiac remodelling results from a hypertensive response we measure systolic and diastolic blood pressure (BP) in CT and ecILK cKO mice at different time points." (PMID 37452166, 2023). "Therefore, ILK deletion in coronary microvasculature presumably leads to microvascular endothelial dysfunction." (PMID 37452166, 2023). "Thus, even a moderate increase in circulating indoxyl sulfate levels can potentiate the effects of decreased ILK levels on the endothelial cell phenotype, which may promote endothelial cell barrier disruption and endothelial dysfunction, facilitating the calcific pathway." (PMID 38534325, 2024). "Although there is limited data on this subject, it has been demonstrated rather earlier that ILK is involved in EC-ECM interaction and endothelial dysfunction." (PMID 23675014, 2007).
neuroblastoma (6 papers, 2006 to 2025). Neuroblastoma (NB) is the most common solid, extracranial childhood tumor. "ILK plays a critical role in neuroblastoma proliferation and survival by regulating PTEN, a key tumor suppressor involved in PI3K/AKT signaling." (PMID 40887471, 2025). "One study using neuroblastoma cell lines found that silencing the LIMS1/ILK pathway reduced cellular proliferation, highlighting its potential as a therapeutic target." (PMID 33048956, 2020). "The SK-N-SH human neuroblastoma cell line, which supports HSV-1 replication, is used to study the role of ILK in HSV-1 infection." (PMID 35350437, 2022).
Obesity (6 papers, 2018 to 2026). Accumulation of substantial excess body fat. "The insulin sensitizing effect of ILK deletion is also associated with improved hepatic steatosis in obesity." (PMID 37383542, 2023). "Overall, these studies highlight the significance of the ECM-integrin-ILK signalling in regulating hepatic insulin action and steatosis in obesity." (PMID 37383542, 2023). "To further elucidate the prolonged use of TF during the early establishment of obesity in vivo and the involvement of ILK, we designed a transgenic mice model with a global ILK downregulation during adulthood (cKDILK)." (PMID 35090553, 2022). "We consider ILK expression levels in WAT to be a biomarker of metabolic malfunction during the development of obesity." (PMID 35090553, 2022). "TF was administered systemically in wildtype (WT) and ILK knockdown (cKDILK) mice during the establishment of obesity based on a high-fat diet (HFD)." (PMID 35090553, 2022). "ILK downregulation in WAT can be considered a biomarker of obesity establishment." (PMID 35090553, 2022). "Together with the present work, our results support the hypothesis that ILK expression is decreased during the development of obesity and WAT transgenic downregulation of ILK (in cKDILK) exacerbates the obesity-related symptoms." (PMID 35090553, 2022). "Despite the central role of ILK in the adaptation to a changing extracellular environment, its role in adipose tissue during the challenge of obesity is unknown." (PMID 33647469, 2021). "ILK is connected with numerous intracellular signalling pathways, such as the mammalian target of rapamycin (mTOR), a serine-threonine kinase, which plays an essential role in autoimmune disorders, obesity and aging." (PMID 30271655, 2018). "HFD-challenged WT allowed us to follow TF consequences on the establishment of obesity, while HFD-challenged cKDILK are a transgenic tool to understand the relevance of ILK." (PMID 35090553, 2022). "Nevertheless, we did carry out a pharmacological strategy to increase ILK expression in vitro and in vivo as a protective approach against obesity that was not used in Bugler-Lamb ́s study." (PMID 35090553, 2022). "•Mice lacking adipocyte ILK had less fat and improved glucose tolerance in obesity." (PMID 33647469, 2021).
osteoarthritis (6 papers, 2020 to 2023). A noninflammatory degenerative joint disease occurring chiefly in older persons, characterized by degeneration of the articular cartilage, hypertrophy of bone at the margins and changes in the synovial membrane. "Simultaneously, GABA, LysoPA(18:1(9Z)/0:0) and L-Targinine, the unique metabolites of RA EP, might participate in neuroinflammation signaling pathway, osteoarthritis pathway, glucocorticoid receptor signaling, ILK signaling, IL-17 signaling and HIF1α signaling." (PMID 35706052, 2022).
Alzheimer disease (5 papers, 2018 to 2022). A progressive, neurodegenerative disease characterized by loss of function and death of nerve cells in several areas of the brain leading to loss of cognitive function such as memory and language. "ILK-related mechanisms are compromised in neurodegenerative diseases (e.g., Alzheimer's disease and Parkinson's disease) characterized by learning and memory deficits." (PMID 31938742, 2020). "For six of these pathways IPA predicted decreased activity: CDC42 signaling, Sumoylation Pathway, Cell Cycle: G2/M DNA Damage Checkpoint Regulation, Neuroprotective Role of THOP1 in Alzheimer’s Disease, PD-1,PD-L1 cancer immunotherapy pathway and ILK Signaling." (PMID 36016386, 2022). "Following the observation of significantly decreased ILK protein levels in streptozotocin (STZ) mice, a model for Alzheimer’s Disease (AD), it has been also suggested that ILK may participate in the pathogenesis of AD." (PMID 35089438, 2022). "This pattern has also been observed in a mouse model for Alzheimer’s disease (AD), where ILK protein levels are significantly decreased in the hippocampus of APP/PS1 mice, which display perturbed neurogenesis and memory deficits, and can be rescued by overexpressing ILK." (PMID 34393704, 2021).
breast tumor (5 papers, 2010 to 2026). "Twist was proven to activate ILK, while in phyllodes breast tumors, ILK was shown to transmit its effects via the Twist pathway." (PMID 36900319, 2023).
diabetic nephropathy (5 papers, 2017 to 2025). "Integrin-linked kinase (ILK) is a key mediator of cytoskeletal organization, cell adhesion, and extracellular matrix remodeling in renal cells, processes that are central to the progression of diabetic nephropathy." (PMID 41375725, 2025). "Furthermore, a recent study implied the protective effects of hesperidin in diabetic nephropathy, possibly through the inhibition of transforming growth factor-β1- (TGF-β1-) integrin-linked kinase- (ILK-) Akt signaling." (PMID 30800211, 2019). "Some other pathways may also participate in the treatment of diabetic nephropathy with Tangzhiqing granules, such as Integrin/ILK and WNT/beta-catenin pathways." (PMID 28163747, 2017). "Furthermore, the studies indicate that hesperidin may offer protective benefits in countering diabetic nephropathy through the inhibition of the signaling pathway involving TGF-β1, ILK, and Akt and improving renal function." (PMID 38234970, 2023).
fibrosis (5 papers, 2016 to 2025). the formation of excess fibrous connective tissue in an organ or tissue in a reparative or reactive process. "In line with previous studies, we found that ILK was overactivated adaptively in sustained profibrogenic factors-induced mice fibrosis model to respond to the up-regulation of SMOC2." (PMID 36935650, 2022). "Among these genes the most expressed canonical pathways were TREM1 signaling, hepatic fibrosis/hepatic stellate cell activation, ILK signaling, IL-17A signaling in airways cells, and production of nitric oxide and reactive oxygen species in macrophages." (PMID 26649052, 2016). "SMOC2 silencing alleviated cardiac fibrosis through inhibition of the ILK/p38 signaling." (PMID 40362577, 2025). "As yet, it is unclear if ILK contributes to cardiac fibrosis by stimulating p38." (PMID 36935650, 2022).
metastatic tumors (5 papers, 2011 to 2024). "In primary tumors from patients diagnosed with HGSOC (stage: 3 + 4, grade: 3), p-ILKSer246 was greater compared to corresponding adjacent ovarian epithelium, demonstrating increased ILK activation, and p-ILKSer246 staining was greatest in metastatic tumors." (PMID 38822429, 2024). "We also discuss the contribution of ILK to therapeutic resistance and examine efforts to target ILK for the treatment of metastatic disease." (PMID 35804980, 2022). "Signaling pathways like NF-kB, ILK and TGF-β, which are essential for epithelial to mesenchymal transition and typically over expressed for mRNA in metastatic tumors, are suggested down regulated for circRNA." (PMID 28279183, 2017).
muscular dystrophy (5 papers, 2008 to 2025). Muscular dystrophy (MD) refers to a group of more than 30 genetic diseases characterized by progressive weakness and degeneration of the skeletal muscles that control movement. "It has been reported that ILK-deficient mice develop a mild muscular dystrophy and exhibit increased susceptibility to stress-induced damage." (PMID 41385533, 2025). "ILK depletion in Caenorhabditis elegans and Drosophila melanogaster leads to muscle detachment of focal adhesion sites, while ILK KO mice presented severe muscular dystrophy and actin cytoskeleton restructuring and displacements of focal adhesion‐related proteins, such as dystrophin and FAK." (PMID 36054466, 2022). "In cardiomyocytes, ILK modulates contraction and, in skeletal muscle cells, it is involved in muscle hypertrophy, protects fibres from stress-induced damage and resembles muscular dystrophy when deleted." (PMID 30271655, 2018). "Mice lacking ILK develop phenotypes resembling those seen in humans and mice lacking the alpha 7-integrin subunit, which lead to muscular dystrophy." (PMID 28845464, 2017).
myeloma (5 papers, 2019 to 2025). "Despite ILK being considered dispensable for myeloma cell survival, inhibiting ILK has previously been shown to reduce the invasive capabilities of myeloma cell lines." (PMID 37568580, 2023). "This combined with the increased abundance of numerous components of the ILK signalling pathway in EMM BMNCs indicates a potential role of this signalling pathway in the migration of myeloma cells to extramedullary sites." (PMID 37568580, 2023).